LHB (luteinizing hormone subunit beta)
Diseases named in the same sentence as LHB in open-access papers (continued):
Sharing a sentence is not in itself a finding about the gene and the disease.
depression (continued). "In rodents, protocols of exposure to high‐intensity stressors (i.e. electric shocks) have been used to model depression and identify adaptations in LHb synaptic transmission and neuronal activity." (PMID 34963191, 2022). "Lateral habenula (LHb) that regulates coping and depression‐like behaviors after aversive stimuli is activated by surgery in the previous study." (PMID 35616407, 2022). "Accordingly, DBS of the LHb can reverse depressive-like behaviors in rodents, reinforcing a role of the LHb in depression." (PMID 33589739, 2022). "Extended and hyperactive LHb aversive signaling can lead to long-lasting plasticity-related changes, resulting in psychiatric disorders such as depression, schizophrenia, and addiction." (PMID 35444521, 2022). "This review covers the roles of the LHb in depression and the process from physiological activation to pathological hyperactivity." (PMID 36386995, 2022). "There has been intense interest recently regarding the role of the LHb in depression and depression-like behaviour, with increased neuronal activity being evident in a variety of models of depression-like behaviour." (PMID 34888704, 2022). "The posterior parietal thalamus where LHb is located showed increased functional connectivity in resting-state functional MRI of patients with subclinical depression." (PMID 36386995, 2022). "It has recently emerged that the LHb is a critical brain region in the pathophysiology of depression." (PMID 36059987, 2022). "The LHb plays a role in the perception of noxious stimuli in injury and depression models, and most LHb neurons have increased firing rates during aversive behavioral states and in response to noxious stimuli." (PMID 35140231, 2022). "Among them, LHb is involved in reward, aversion, addiction and depression through descending interactions with several brain structures, including the ventral tegmental area (VTA)." (PMID 35093138, 2022). "Ketamine, an NMDAR antagonist, can rapidly relieve symptoms of depression by blocking the bursting activity of LHb neurons." (PMID 36187288, 2022). "This will aid in understanding the detailed mechanisms of LHb in depression and the screening of potential antidepressant targets." (PMID 36386995, 2022). "Hyperactivity of LHb is found in both rodent models of depression and human patients with depression." (PMID 36059987, 2022). "The important role of the LHb in the pathophysiology of depression is largely due to its rich projection neurons." (PMID 36386995, 2022). "This novel insight can help to explain the otherwise seemingly disparate LHb behavioral results, and it can be used to guide future LHb analyses, especially those relevant to clinical conditions such as depression." (PMID 33712440, 2021). "More direct evidence of the involvement of the LHb in psychiatric disorders in humans comes from deep brain stimulation (DBS) of the LHb that has potential therapeutic effects in treatment-resistant depression, bipolar disorder, and schizophrenia." (PMID 34251338, 2021). "Since LHb was recently discovered as the key brain region in the pathophysiology of depression, a surge in interest over CaMKII has uncovered its role in regulating several signal transduction pathways associated with learning and memory." (PMID 33143210, 2020). "Since it is a critical crossroad that influences brain responses to and encoding of aversive stimuli, such as stress, pain, anxiety, or pleasurable stimuli such as reward, the LHb has been correlated with major depressive disorders." (PMID 33143210, 2020). "Recently, the LHb has been gaining more attention because of its role in psychiatric disorders such as anxiety and depression." (PMID 30804373, 2019). "Along the same line, the LHb, in particular via the mesohabenular pathway, has attracted significant attention due to its role in addiction, reward, aversion, anxiety and depression." (PMID 31481399, 2019).
depression (continued). "Further, LHb bursting plays an important role in the pathophysiology of depression that requires both NMDARs and low-voltage-sensitive T-type calcium channels (T-VSCCs)." (PMID 31374046, 2019). "Considerable efforts will be necessary to clarify the hierarchical sequence of events that are responsible for aberrant LHb activity in depression." (PMID 30083090, 2018). "It is yet to be determined how long ketamine-induced suppression of LHb bursting activity persists in these depression models." (PMID 30425634, 2018). "Central to reward processing, learning and goal directed behavior, the LHb has emerged as a critical regulator of the behaviors that are impaired in depression." (PMID 30581384, 2018). "LHb hyperactivity seems to be the common finding in rodent models of depression and in humans with depression." (PMID 30425634, 2018). "Specifically, we detected a reduction in DMN connectivity following LHb perturbation with an inhibitory opsin in a rat model of treatment-resistant depression." (PMID 29581421, 2018). "Consistent with such clinical evidence indicating LHb dysfunction in depression, pre-clinical studies also described increased metabolic activity in rodent models of depression." (PMID 30083090, 2018). "Our study is the first to provide evidence for a causal relationship between LHb modulation and connectivity alterations in the DMN—two important factors of depression pathophysiology and, potentially, therapy." (PMID 29581421, 2018). "In the following paragraphs, we will summarize the latest advances in restoring LHb neuronal function and present new ideas for potential therapeutic interventions in depression." (PMID 30083090, 2018). "The majority of the studies reported here examined tonic activity of LHb in the context of depression." (PMID 30083090, 2018). "In this review article, we will discuss pre-clinical and clinical evidence highlighting the role of LHb and its cellular adaptations in depression." (PMID 30083090, 2018). "Overall, it appears that the LHb exhibits the same pathological changes in response to both depression and pain." (PMID 28270756, 2017). "In this study, we used FST and SPT to determine the effect of LHb lesions on depression behaviors in CCI rats." (PMID 28270756, 2017). "In animal model of depression, increased LHb neuronal activity drives the excitation of GABAergic neurons in the rostromedial tegmental nucleus, which reduces dopaminergic activity and is potentially involved in the pathophysiology of depression." (PMID 28420875, 2017). "Several lines of evidence from studies in animal models and humans suggest that the MHb plays a major role in nicotine addiction, whereas dysregulation of the LHb is likely to be involved in several psychiatric disorders, including depression." (PMID 28420875, 2017). "Because dysregulation of DA has been implicated in psychiatric disorders, including addiction, schizophrenia, and depression, the LHb has gained popularity as a potential therapeutic target for drug addiction and depression-like behavior." (PMID 27785462, 2016). "The role of LHb in psychiatric disorders such as depression is well known, while the role of MHb is neglected." (PMID 26462807, 2016). "The vast literature devoted to LHb indicates that these nuclei have a relevant role in different brain functions, and dysfunctions (e.g., depression and addiction)." (PMID 26779042, 2015). "The LHb directly innervates these transmitter systems, indicating a central role for this brain region during depression and antidepressant treatment." (PMID 24339877, 2013). "The aim was to clarify the role of the LHb in depression and antidepressant treatment at a molecular level." (PMID 24339877, 2013). "While the link between LHb hyperactivity and major depression disorder (MDD) receives the most scientific attention, elevated activity in the MHb and IPN have also been linked to depression." (PMID 24478666, 2013).
depression (continued). "This, together with other evidence, suggests a potential etiological role of LHb hyperactivity in depression, which is characterized by cognitive indecision and psychomotor retardation." (PMID 23840355, 2013). "This 1:1 translational step resulted from the excellent validity of our cLH animal model, but also from other animal and human findings to date, all of which suggest that the LHb has to be downregulated to cure depression." (PMID 23828711, 2013). "The laser-capture microdissected LHb RNA was subjected to microarray analysis to identify transcriptomic changes related to depression and antidepressant treatment." (PMID 24339877, 2013). "The striking effect of LHb glutamatergic activation on memory consolidation begs the question of whether LHb activity could be contributing to the cognitive deficits that often accompany depression in patients." (PMID 40799491, 2025). "Therefore, genetic removal of MDGA1 prevents the LHb from signaling the onset of depression during stressful events, providing a novel therapeutic target for limiting the effects of stress on genesis of depressive states." (PMID 39897557, 2025). "One notable aspect of LHb physiology is its position at the interface between emotion and higher order cognitive processes like learning and memory, especially given the high prevalence of cognitive impairment in patients with depression." (PMID 40799491, 2025). "In fact, LHb burst firing has been shown to drive depression by artificial stimulation experiments in rodents, and this burst firing is considered a major target of ketamine antidepressant therapy due to ketamine’s action in reducing burst firing in hyperactive LHb neurons." (PMID 40799491, 2025). "Taken together, these results indicates that the interaction between MDGA1 and Nlgn2 in the LHb may play roles in the regulation of LHb function in the development of stress-induced depression." (PMID 39897557, 2025). "Interestingly, in rodent and zebrafish models of depression, the LHb has been highlighted as the major region of hyperactivity associated with depression." (PMID 40799491, 2025). "Given the known link between habenular network hyperactivity and depression, our findings support the idea that disrupted LHb activity may play a direct role in mediating these cognitive impairments through maladaptive neural plasticity." (PMID 40799491, 2025). "LHb is a key regulatory area of motivation, a critical region for recognizing signals of punishment and reward, and is involved in the pathogenesis of affective disorders including depression and bipolar disorder." (PMID 39596543, 2024). "However, the precise spike patterns of LHb neurons projecting to different brain regions during depression, their roles in depression development, and BLT's therapeutic action remain elusive." (PMID 38863324, 2024). "Accumulating evidence indicate that LHb hyperactivity plays an instrumental role in pathophysiology of depression and possibly other mood disorders and substance use disorders, thus LHb is gaining interest as a potential target for neuromodulation and antidepressants." (PMID 38509283, 2024). "In experience-dependent plasticity, LHb maturation is affected by early life stress on postnatal days 10–20 (P10-20) in mice, leading to late effects of hyperactivity in the LHb and anxiety or depression in adulthood." (PMID 39605808, 2024). "CRF may further promote depression by activating the LHb and amplifying cholinergic neurotransmission, another key feature of major depressive disorder." (PMID 39150032, 2024). "The LHb has been described as pathologically hyperactive in major depressive disorder." (PMID 39150032, 2024). "Acute stress transforms LHb signals in such a way that reward leads to activation of this structure, similar to punishment or missed reward, which can disrupt the perception of reward signals and contribute to the development of depression under stress." (PMID 39596543, 2024).
depression (continued). "Therefore, there is a converging consensuses that the LHb is a central junction linking emotional and circadian disorders and that hyper-activation of the LHb triggers sleep disturbances and depression." (PMID 37768984, 2023). "Notably, they also found that selective LHb lesions reversed depression symptoms and hyperalgesia in a rodent model of chronic pain." (PMID 37987455, 2023). "Hence, we utilised the maternal separation (MS) model of depression to study how early life stress alters LHb physiology and depressive behaviour in adult mice." (PMID 36371544, 2023). "In this study, we observed an immediate (within seconds to minutes) alleviation of depressive-like symptoms with a high-response rate under DBS targeting the LHb (LHb-DBS) in two rat models of depression, Wistar Kyoto (WKY) and lipopolysaccharide (LPS)-treated rats." (PMID 37261976, 2023). "In various animal models of depression, the LHb is the only brain region that shows consistently increased activity, and a large body of evidence from animal models and human studies suggests a relationship between the LHb and various psychiatric disorders, particularly major depression." (PMID 36624089, 2023). "Based on these connections, the LHb modulates neurotransmitter systems including DA and 5-HT, and participates in various physiological and pathophysiological processes such as anxiety, depression, reward-aversion and addiction." (PMID 35145415, 2022). "Importantly, LHb neurons become hyperactive in both depressed humans and animal models of depression, and normalizing LHb activity with pharmacological or electrical approaches rescues behavioural symptoms." (PMID 34963191, 2022). "The LHb, known for its role in mediating midbrain aminergic structures with forebrain limbic areas, is increasingly being investigated as a potential neural hub for the emergence of major depression disorder." (PMID 35990727, 2022). "In addition, long-term perturbation of LHb or MHb leads to the expression of depression-like behavior or increased anxiety." (PMID 35437264, 2022). "The lack of extracellular ATP activates LHb-projecting mPFC neurons through disinhibition of mPFC GABAergic interneurons, resulting in depressive-like behaviors in a mouse model of depression induced by CSDS or IP3R2-null mutation." (PMID 36386995, 2022). "Also, the yet unexplored LHb function in sleep appears relevant due to the relation between sleep and stress exposure, and because sleep disturbances are key features of pathologies involving LHb dysfunction such as depression and schizophrenia." (PMID 35308564, 2022). "Not surprisingly, LHb dysfunction contributes to a myriad of cognitive, learning, and affective impairments associated with depression, anxiety, psychosis and drug addiction." (PMID 35308564, 2022). "Increased LHb-DRN pathway activity may serve as one of the underlying mechanisms of the comorbidity of pain and depression." (PMID 36386995, 2022). "As a prodromal state and significant inducer of depression, early-stress-induced LHb burst firing is a precursor to depressive symptoms, which could perhaps improve indirect inhibitory input to downstream regions and release neuropeptides." (PMID 36386995, 2022). "Finally, modulation of the LHb with DBS has been demonstrated to be an effective therapy in a patient with treatment resistant depression (TRD)." (PMID 35784832, 2022). "The recent results showing that environmental illumination conditions directly influence the LHb capacity to signal stress through a retino-thalamo-habenular circuit, and participates in the effect of light therapy in depression, is a first step toward this goal." (PMID 35308564, 2022). "The cluster discharge of the LHb in rats is sufficient for the occurrence of depression." (PMID 36064380, 2022).
depression (continued). "Furthermore, a couple of clinical evidence based on deep brain stimulation in patients with treatment-resistant depression suggested the LHb as a potential therapeutic target for major depressive disorder." (PMID 35221943, 2021). "The LHb is a brain region that is crucial for regulation and resilience in depressed patients, but the molecular determinants responsible for the key role of the LHb in depression remain elusive." (PMID 33436036, 2021). "The LHb has shown consistent hyperactivity in multiple animal models of depression-like phenotypes." (PMID 34251338, 2021). "However, our understanding of the mechanisms by which chronic alcohol administration and withdrawal as well as depression increase LHb spike output and glutamatergic transmission is incomplete." (PMID 33143210, 2020). "Finally, a seminal single case study reported successful remission from pharmaco-resistant depression after targeting the LHb with local delivery of high frequency stimulation." (PMID 30083090, 2018). "In addition, the use of Designer Receptor Exclusively Activated by Designer Drug (DREADD) technology has produced some exciting information pertaining to LHb circuits relevant to depression, aversion, motivation and stress reactivity." (PMID 30581384, 2018). "Not surprisingly, LHb dysfunction contributes to a myriad of cognitive, learning, emotional and social impairments associated with depression, anxiety, psychosis and drug addiction." (PMID 30425634, 2018). "Much progress has been made to emphasize the role of the LHb in the pathogenesis of depression." (PMID 30356828, 2018). "Although the studies covered in this review provide evidence in support of the LHb hyperexcitability in the development and remediation of depression, more work is needed to consolidate this hypothesis." (PMID 30581384, 2018). "It is also likely that different modulating burst firing patterns induced by multiple molecular mediators may provide new sophisticated tools that hold the key to alleviating LHb dysfunction in depression." (PMID 30581384, 2018). "Moreover, deep brain stimulation of the LHb in humans has been shown to alleviate chronic unremitting depression in treatment resistant depression." (PMID 30581384, 2018). "Moreover, the antidepressant effects of ketamine in treatment-resistant major depression have been associated with decreased glucose utilization and metabolism in the habenula suggesting that antidepressant effects of ketamine may be related to reduction of LHb neuronal activity." (PMID 30425634, 2018). "LHb inhibition, as detailed above, is a promising therapeutic principle for depressive disorders." (PMID 29581421, 2018). "Together, our results suggest that increased activity of the LHb-DRN pathway may be a common neurobiological mechanism underlying pain and depression, which have provided explanation for their coexistence." (PMID 28270756, 2017). "In rat models of depression, the activity of the LHb is increased." (PMID 28270756, 2017). "There is also evidence that LHb neuronal activity is increased in patients with depression." (PMID 28270756, 2017). "More recent studies in humans have corroborated the notion of LHb involvement in the reward system, and, interestingly, two case reports have since been published (2010, 2013) showing remission of major depression under DBS of the LHb." (PMID 27092042, 2016). "The role of the LHb in mediating depression-like behaviors may thus be related to its roles in punishment, and aversion." (PMID 27482535, 2016). "This hypothesis was strengthened by high-resolution MRI studies in humans, demonstrating reduced LHb volume in bipolar disorder and major depressive disorder." (PMID 24376408, 2013). "Unraveling the role of the LHb in depression and treatment might lead us to new molecular targets involved in depression pathology and novel treatment strategies." (PMID 24339877, 2013).